LRP5 (LDL receptor related protein 5)
Diseases named in the same sentence as LRP5 in open-access papers (continued):
Sharing a sentence is not in itself a finding about the gene and the disease.
tumor (continued). "For example, an LRP5 activating mutation and a PEAK1 mutation originally found solely in a metastasis were subsequently detected within the primary tumor by UDS-UMI/UDG and estimated to be present within the same rare subclone comprised of only 2% of tumor cells." (PMID 38321573, 2024). "For the role of LRP5 in tumor cells, there are two types of research results in the past." (PMID 38706907, 2024). "Soluble LRP5 also reduces 143B cell tumour growth in nude mice." (PMID 38928468, 2024). "Although osteocytes could often present innate anti-tumor capabilities 11, the activation of Wnt signaling by the overexpression of Lrp5, a Wnt coreceptor, and β-catenin enhanced their anti-tumor action." (PMID 36923539, 2023). "We have previously shown that overexpressing Lrp5, β-catenin, Snail, or Akt converted many types of bone cells such as mesenchymal stem cells (MSCs), osteoblasts, osteocytes, and osteoclasts into induced tumor-suppressing (iTS) cells 3-7." (PMID 35547745, 2022). "Further investigation of the regulatory mechanism may provide better insight into the precise roles of Hsp90ab1, MSN, CD44, and FN1 in the anti-tumor action of Lrp5 CM." (PMID 34976221, 2022). "Finally, the coreceptors LRP5 and LRP6 are key receptors for the activation of canonical WNT signaling, and specific deletion of LRP5 and LRP6 in DCs is associated with delayed tumor progression and enhanced host antitumor immunity." (PMID 36358276, 2022). "Besides the suppression of tumor progression, Lrp5 CM stimulated osteoblast differentiation and inhibited osteoclast differentiation." (PMID 34976221, 2022). "Furthermore, effective anti-cancer strategies involving LRP5-directed therapies remains a current conundrum, as Wnt signaling orchestrates normal bone formation and LRP5 expression in osteoclasts results in tumor-suppression." (PMID 35204808, 2022). "Besides osteoblast-derived CM, EO771 tumor cell-derived CM by the overexpression of Lrp5, MSN, or OPN reduced the MTT-based viability of EO771 parent cells." (PMID 34976221, 2022). "The in vitro results so far support the tumor-suppressing capability of Lrp5 CM." (PMID 34976221, 2022). "The western blot results showed that in EO771 cells, A5 CM downregulated tumor-promoting genes such as Sclerostin, Lrp5, β-catenin, MMP9, Runx2, TGFβ, and Snail and elevated the level of an apoptosis marker, cleaved caspase 3, more substantially than did Y4 CM." (PMID 34230453, 2021). "Notably Lrp5, β-catenin, Snail and Akt promoted tumor progression when they were overexpressed in tumor cells whereas MSC CMs with their overexpression acted as tumor-suppressing agents." (PMID 33859739, 2021). "The tumor-suppressing action of osteocyte-derived CM to the mammary fat pad, bone, and brain indicates that tumor-suppressing proteins are enriched in osteocyte-derived CM and this enrichment is amplified by the overexpression of Lrp5, β-catenin, and IL1ra." (PMID 33802279, 2021). "In addition to the tumor-driven reduction in BV/TV, we also observed a reduction in BV/TV by deletion of Lrp5 in osteocytes." (PMID 34230453, 2021). "Collectively, our results reveal opposing roles of the Lrp5/β-catenin axis in tumor cells and osteocytes; these roles impact the metastatic progression of cancer and potentially provide an explanation for the limited success in targeting this signaling axis in advanced cancers." (PMID 34230453, 2021).
tumor (continued). "The result indicates that Lrp5 in osteocytes is necessary for inducing loading-driven bone formation, but it is not required for causing loading-driven tumor suppression." (PMID 33450808, 2021). "Notably, silencing Lrp5 in tumors inhibited tumor progression, while silencing Lrp5 in osteocytes in conditional knockout mice promoted tumor progression." (PMID 34230453, 2021). "Thus, our results suggest that the Lrp5/β-catenin axis activates tumor-promoting signaling in tumor cells but tumor-suppressive signaling in osteocytes." (PMID 34230453, 2021). "The Lrp5 overexpression-induced changes in the expression levels of these proteins in osteocyte CM could contribute to the inhibition of tumor progression." (PMID 34230453, 2021). "Additionally, the levels of tumor-promoting genes (Lrp5, MMP9, Runx2, and Snail) were increased by TGFβ and CXCL5, while they were reduced by TPM4, ANXA6, and Trail." (PMID 34230453, 2021). "Lrp5-overexpressing MSCs were also shown to act as anti-tumor agents." (PMID 33802279, 2021). "While mechanical loading can suppress tumor growth, the question is whether Lrp5 mediates loading-driven tumor suppression." (PMID 33450808, 2021). "However, little is known about the role of Lrp5-mediated Wnt signaling in loading-driven tumor suppression." (PMID 33450808, 2021). "The Lrp5-independent mechanism was supported by the observation that regardless of Lrp5 presence in osteocytes, knee loading inhibited tumor growth in the mammary fat pad and bone loss in the tumor-invaded tibia." (PMID 33450808, 2021). "The overexpression of Lrp5 in osteocytes granted the tumor-suppressing capability to osteocytes." (PMID 33450808, 2021). "As a coreceptor of Wnt signaling, Lrp5 in tumor cells may be regulated by dopamine to induce tumor-suppressing capabilities." (PMID 34031366, 2021). "Notably, although knee loading suppressed the growth of tumors in the tibia, the tumor-induced damage was more severe when Lrp5 was deleted." (PMID 33450808, 2021). "X-ray images showed that the co-injection of osteocytes with and without Lrp5 overexpression as well as the systemic administration of β-catenin-overexpressing CM suppressed tumor-driven bone loss." (PMID 33802279, 2021). "Notably, Lrp5 overexpression in osteocytes enhanced tumor suppression, and osteoclast development was inhibited by chemerin." (PMID 33450808, 2021). "Taken together, the role of Lrp5 in Wnt signaling differs in tumor cells and osteocytes, and thus the therapeutic inhibition of Lrp5/Wnt signaling may weaken the intrinsic tumor-suppressing capability of osteocytes." (PMID 33450808, 2021). "Overexpression of Lrp5 in osteocytes enhanced the shrinkage of tumor spheroids." (PMID 33450808, 2021). "However, the depletion of LRP5 had a similar effect to that of LRP6 on tumor growth in a xenograft model." (PMID 29854300, 2018). "This hypothesis was confirmed in vivo in a xenograft model in which the depletion of LRP5 or LRP6 delayed tumor growth." (PMID 29854300, 2018). "Moreover, a dominant negative LRP5 mutant reduced tumor and metastasis formation in an experimental OS mouse model." (PMID 25992885, 2015). "We show that these cell types are substantially inter-dependent, since the MMTV LTR drives expression of Wnt1 ligand in luminal cells, whereas the functional Wnt1-responsive receptor (Lrp5) is expressed by basal cells, and both molecules are necessary for tumor growth." (PMID 21541292, 2011). "Since we also observe luminal cells that can serve as tumor-initiating cells, we tested the hypothesis that these cells might also express Lrp5 protein." (PMID 21541292, 2011). "These tumors are not all basaloid, they include tumors of many classes, which suggests that the Lrp5-dependent growth pathway could become viable in many candidate tumor precursor cell types." (PMID 19672307, 2009).
tumor (continued). "The tumor-associated shorter transcript LRP5Δ666–809 contained an in-frame deletion of 142 amino acids (Δ666–809), encompassing the third YWTD β-propeller domain between the second and third epidermal growth factor repeats of LRP5." (PMID 18044981, 2007). "Interestingly, OPN exhibits context-dependent functionality: in tumor cells, it promotes tumorigenesis and survival in circulation, whereas in Lrp5-overexpressing osteoblasts, OPN may exert anti-proliferative effects on tumor cells." (PMID 41596432, 2026). "In GC, overexpression of Wnt ligands (Wnt2, Wnt3, and Wnt5A) and receptors (FZD7 and LRP5/6) is associated with more advanced disease, poorer prognosis, and elevated metastatic potential, while β-catenin and reduced APC expression further underline more aggressive tumor behavior." (PMID 40943055, 2025). "LRP5 gene fusion with UBE3C results in the loss of the DKK-1 inhibitory domain; in a study of head and neck cancers, this fusion was found to stimulate Wnt/β-catenin signaling and upregulate MYC, CCND1, TCF4, and LEF13 expression, resulting in tumor cell proliferation." (PMID 40940800, 2025). "Therefore, the role of LRP5 in the progression of cancer is complicated and may depend on specific tumour microenvironment or the heterogeneity of cancers." (PMID 34997691, 2022). "Notably, dopamine downregulated Lrp5 via DRD1 in tumor cells." (PMID 34031366, 2021). "Therefore, we first observed that Lrp5 was downregulated by dopamine and FP in tumor cells." (PMID 34031366, 2021). "Herein, we examined whether Lrp5 would regulate the tumor-suppressing capability of MSCs." (PMID 33859739, 2021). "Importantly, when the WNT2/LRP5/LRP6 canonical Wnt signature was used for analysis using STAD tumor data, the modest correlation with TAMs (compare lines 2b, 6b) and M2 markers (compare lines 4b, 8b) was lost, favoring a role for the non-canonical Wnt pathway in macrophage infiltration." (PMID 33869179, 2021). "Notably, the observed anti-tumor effect was enhanced by the overexpression of Lrp5 in osteocytes." (PMID 33802279, 2021). "However, in the families carrying LRP5 gain‐of‐function mutations, increased incidence of cancer is not reported, and tumor developments in Sost‐ or Dkk1‐deficient animals are not observed." (PMID 26941261, 2016). "To elucidate how LIMA1 mediates the tumor-suppressive effects of LRP5-overexpressing osteocyte-derived CM, we generated an MLO-A5 osteocyte model with LIMA1 knockdown combined with LRP5 overexpression using plasmid and shRNA transfection." (PMID 41596426, 2026). "Deregulation of pathways including Wnt/β-catenin (e.g., LRP5, β-catenin overexpression) and PI3K/Akt has been shown to promote tumor cell survival and adaptation in the bone niche." (PMID 41596432, 2026). "Through these combined actions, LRP5-activated osteocytes, via LIMA1 and MYO5B, simultaneously suppress tumor growth, limit osteolysis, and alleviate the immunosuppressive milieu within the bone metastatic niche." (PMID 41596426, 2026). "In murine tumor samples, we validated that CRS also promotes expression of LRP5 and β-catenin in tumors, and this effect is reversed by gut sterilization." (PMID 40038255, 2025). "WNT7A-FZD6/FZD3+LRP6/LRP5, critical components of the canonical Wnt signaling pathway, were exclusively expressed in STAR + cells and tumor cells." (PMID 40098624, 2025). "Protein expression of ZFP36, LRP5, β-catenin and stemness factor NANOG in tumor samples was then analyzed." (PMID 40038255, 2025). "While these findings advance our understanding of rtSPIRE1’s involvement in PI3K/AKT pathway modulation and LRP5 interactions, further exploration using advanced animal models or tumor organoids could offer deeper mechanistic insights into its functions within the tumor microenvironment." (PMID 40713830, 2025).
tumor (continued). "HMGB2 in POSTN+ fibroblasts is predicted to bind to PLD2, LRP5, MYLK, and CD44 on tumor cells, regulating downstream genes, including BIRC5, CCNA2, CCNB1, CCNB2, CDC20, and MKI67, which are related to the cell cycle." (PMID 38519500, 2024). "In TNBC, the Wnt signaling pathway is hyper-activated and promotes tumor progression through the overexpression of Frizzled and its co-receptors, LDL Receptor-Related Protein 5 (LRP5) and LDL Receptor-Related Protein 6 (LRP6)." (PMID 39201539, 2024). "By implanting BALB/c nude murine models in situ, the function of SOST on tumor growth was investigated, followed by immunofluorescence double staining of SOST and LRP5/6." (PMID 35785219, 2022). "In the present study, we confirmed that activation of LRP5 in CRC cells increased the cellular proliferation, migration and enhanced chemoresistance in vitro, and promoted the tumour growth in vivo via activating the canonical Wnt/β‐catenin pathway." (PMID 34997691, 2022). "Of note, Kdm3a is a histone demethylase to regulate the availability of chromatin, while Lrp5 is a co-receptor of Wnt signaling and MMP9 is a matrix metalloproteinase to promote tumor migration." (PMID 35547745, 2022). "Silencing CD44 and FN1 in EO771 cells and MDA-MB-231 cells downregulated MTT-based viability as well as the expression of Lrp5, MMP9, Runx2, and Snail in EO771 cells, whereas their silencing significantly suppressed MSN-induced tumor inhibition." (PMID 34976221, 2022). "Collectively, the result supported the notion that the activation of Wnt signaling by the overexpression of Lrp5 and β-catenin, as well as the treatment with BML284, granted osteoblast-derived CM a tumor-suppressing capability." (PMID 34976221, 2022). "Tumour cells present in the TME, for example, express FZD8 and LRP5/6 coreceptors known to interact with WNT4 ligand." (PMID 34841720, 2021). "We observed that Lrp5-overexpressing osteocyte-derived CM inhibited the proliferation and invasion of EO771 tumor cells, as determined by EdU incorporation and Transwell assays, respectively." (PMID 34230453, 2021). "In cytokine and chemokine array analyses the overexpression of Lrp5 reduced the levels of several tumor-promoting factors in CM, including CXCL2, GM-CSF, IL6, LIF, DLK1 and MRP with an increase in IL27, a tumor-suppressing cytokine." (PMID 33859739, 2021). "In contrast to Lrp5-overexpressing osteocytes, Lrp5-overexpressing astrocyte-derived CM promoted the viability and migration of EO771 tumor cells, and the level of MMP9, Runx2, and Snail in EO771 cells were upregulated." (PMID 33802279, 2021). "Deletion of LRP5 and LRP6 in dendritic cells markedly delayed tumor growth and enhanced host antitumor immunity by blocking the Wnt pathway." (PMID 31164891, 2019). "Contrarily, tumor immune evasion by Dickkopf-related protein 2 (DKK2), with LRP5, is thought to act independently of the Wnt/β-catenin pathway, via inhibition of STAT5 signaling." (PMID 31167446, 2019). "Upon conditional knockout of the Wnt co-receptors LRP5 and LRP6 on DCs, DC-mediated anti-tumor immunity is enhanced, ultimately resulting in delayed tumor growth." (PMID 31616443, 2019). "We found a predominant cytoplasmic expression, both of LRP5 and LRP6, which resulted in the overexpression in 48.6% (107/220) and 44.5% (98/220) of tumor samples, respectively." (PMID 31336689, 2019). "In particular, some tumor samples had high levels of LRP6 RNA and low levels of LRP5 RNA (top left corner), whereas the opposite pattern was observed for others (bottom right corner)." (PMID 29854300, 2018). "We found that the depletion of LRP5, LRP6 or STK40 slowed tumor growth in an MDA-MB-468-derived xenograft model." (PMID 29854300, 2018).
tumor (continued). "Depletions of LRP5, LRP6 or STK40 delayed tumor growth to similar extents in a statistically different manner." (PMID 29854300, 2018). "Conditional knockout of Wnt co-receptors LRP5 and LRP6 on DCs, on the other hand, enhanced DC-mediated anti-tumor immunity leading to delayed tumor growth." (PMID 30619378, 2018). "Accordingly, conditional deletion of β-catenin or LRP5/6 in DCs markedly reduces regulatory T cell responses with increased effector CD8 T cell responses, leading to suppression of tumor growth." (PMID 27833613, 2016). "A previous study showed that the majority of tumor initiating cell activity for tumors arising in this mouse model were CD61-positive; we found that Lrp5-positive cells also express CD61, so these two cell surface markers are co-expressed." (PMID 21541292, 2011). "Rather than exclusively inhibiting tumor cell-intrinsic pathways, our strategy directly modulates the bone microenvironment through osteocytic LRP5 overexpression, thereby reprogramming the “soil” in which metastatic cells reside." (PMID 41596426, 2026). "Finally, rtSPIRE1 stabilizes LRP5 by inhibiting its ubiquitination, activating the PI3K/AKT/mTOR signaling pathway to promote tumor progression." (PMID 40713830, 2025). "In the bone microenvironment, the result herein suggests the possibility of building a positive feedback loop, as opposed to a vicious cycle, in which Lrp5 CM inhibits the progression of tumor cells and strengthens the anti-tumor action of osteoclasts." (PMID 34976221, 2022). "While Lrp5 CM, mostly analyzed in this study, contains a spectrum of secretomes, we focused on the role of three moonlighting proteins, OPN, Hsp90ab1, and MSN, for tumor suppression." (PMID 34976221, 2022). "The selected protumorigenic genes (Lrp5, MMP9, Runx2, TGFβ, and Snail) were downregulated in Oct4 CM-treated 4T1.2 parental cells, while they were elevated in Oct4-overexpressing tumor cells and reduced in Oct4-silenced tumor cells." (PMID 35547745, 2022). "Further analysis showed that LRP5 and LRP6 membrane receptors presented lower expressions in tumor cells of the model + sh-SOST group than that of the model + sh-NC group, demonstrating that SOST suppression could decrease the expressions of LRP5 and LRP6." (PMID 35785219, 2022). "Moreover, the protein levels of LRP5, LRP6, TCF-4, and LEF1 in the tumor were also significantly down-regulated by AR decoction or oxaliplatin treatment in xenograft mice." (PMID 34991661, 2022). "The growth curve showed that LRP5‐ACT HCT‐116 cells could grow faster and form larger tumours than that of the NC‐ACT ones, suggesting activation of LRP5 obviously accelerated the tumour growth in vivo." (PMID 34997691, 2022). "In terms of the genes that are exclusively affected by tumor-specific somatic TE insertions, we also observed the enrichment of affected genes in the cancer pathway (due to tumor-specific TE insertions in genes such as COL4A6, PLCB4, ARNT2, LRP5, NCOA3, and CTNNA2)." (PMID 35013466, 2022). "By contrast, MSCs did not present the innate anti-tumor actions but the overexpression of Lrp5 converted them into anti-tumor agents by reducing the MTT-based viability and downregulating MMP9, Runx2, and Snail, as well as N-cadherin in EO771 cells." (PMID 33802279, 2021). "The results so far showed the beneficial role of Lrp5 in osteocytes in the tumor-invaded tibia regardless of knee loading." (PMID 33450808, 2021). "Taken together, the result supported the anti-tumor action of extracellular Hsp90ab1, and not Hsp90aa1, in regulating Lrp5, Runx2, TGFβ, and IL27 in tumor cells." (PMID 34830748, 2021). "Collectively, these results indicated that Lrp5 but not Lrp6 altered the tumor-suppressive capability of osteocytes." (PMID 34230453, 2021).